ATRX (ATRX chromatin remodeler)
Diseases named in the same sentence as ATRX in open-access papers (continued):
Sharing a sentence is not in itself a finding about the gene and the disease.
glioma (continued). "A recent study provides a connection between the role of ATRX as an epigenetic regulator and glioma development." (PMID 33348922, 2020). "Consistent with the fact that the mutation of IDH1 and ATRX is associated with prolonged survival in glioma, our result showed that the SNPs in IDH1 and ATRX exerted a higher somatic mutation burden in the low‐risk group than in the high‐risk group." (PMID 32301283, 2020). "ATRX, one of the critical molecular biomarkers guiding the classification and diagnosis of glioma, plays a vital role in chromatin remodeling and the maintenance of genome and telomere stability." (PMID 33194637, 2020). "High BACE2 expression was related to wild‐type IDH1 in glioma patients, while low BACE2 expression was associated with other features, including MGMT promoter methylation, 1p/19q codeletion, TERT loss and ATRX mutation." (PMID 31856384, 2020). "Cluster I was characterized by enrichment of mutations in IDH1 (52%, FDR = 1.42 × 10−8) and ATRX (27%, FDR = 0.0232), consistent with their predominance in glioma samples." (PMID 33194713, 2020). "Taking the findings together, our study implies that the miR-1269a/ATRX axis is a novel therapeutic target of glioma." (PMID 33194637, 2020). "The frequency of ATRX loss was the highest in WHO II astrocytoma (57.1%), while PHH3 and Ki67 were both exhibited high expression rate in high grade gliomas (WHO III and IV)." (PMID 32047544, 2020). "Mutational analysis of TCGA data set revealed that SNPs in IDH1, ATRX, PTEN and EGFR were significantly associated with risk status in glioma." (PMID 32301283, 2020). "The ATRX status has been found to be one of the critical markers that define the molecular classification of gliomas." (PMID 32047515, 2019). "We also compared GSCs derived from IDH-mutant, ATRX-mutant (08-0537) and IDH-mutant, ATRX wild-type (TS 603) gliomas, finding increased nuclear G4s in the former by BG4 immunofluorescence." (PMID 30808951, 2019). "Moreover, multiple CNAs recurrently featured in ATRX-deficient glioma mobilize established oncogenic and/or tumor suppressive loci, including MYC and CDKN2A2, implying that such structural abnormalities may contribute to the malignant evolution of this inexorably progressive cancer." (PMID 30808951, 2019). "In summary, we firmly implicate G4 secondary structure as a defining characteristic of ATRX-mutant glioma, one that drives disease-relevant genomic instability and presents opportunities for tangible therapeutic advancement." (PMID 30808951, 2019). "Aberrations within ATRX sequence or alterations of its expression were found in various cancers including glioma, neuroblastoma, osteosarcoma, colorectal cancer or lung cancer." (PMID 31500094, 2019). "Evidently, the overall survival of glioma patients can be affected by many important clinical and genetic factors, such as age, tumor grades, ATRX status, IDH1/2 status, telomerase reverse transcriptase (TERT) status, and so on16,17." (PMID 30936423, 2019). "Taken together, these data firmly implicate GNA13 and downstream RhoA signaling, along with potentially other ATRX-responsive genes, in the process of ATRX-dependent glioma cell migration." (PMID 29535300, 2018).
glioma (continued). "Another study that attempted to further sub-classify the 5 integrated WHO glioma groups by ATRX and TERT promoter status showed that ATRX alterations were enriched in TERTp-wt GBM." (PMID 30333046, 2018). "In order to better understand the apparent role of ATRX as an ALT suppressor in cancer, we have generated clonal, ATRX-knockout human high-grade glioma-derived cell lines." (PMID 30226859, 2018). "The migratory behavior of diffusely infiltrating gliomas, including ATRX-mutant astrocytomas, represents a major determinant of their malignant potential, effectively rendering them incurable by surgical resection." (PMID 29535300, 2018). "In contrast, here, we have identified two ALT-negative glioma cell lines–U-251 and UW479 –in which ATRX loss is sufficient for the generation of ALT hallmarks de novo." (PMID 30226859, 2018). "In parallel, we performed immunohistochemical studies on ten IDH-mutant gliomas with known ATRX expression status." (PMID 29535300, 2018). "In an attempt to identify additional glioma cell lines that show ALT hallmarks after ATRX loss, we stably knocked down ATRX in SF295, CHLA-200, and KNS42, cell lines in which we were unable to recover CRISPR-mediated ATRX knockouts." (PMID 30226859, 2018). "Although significant advances have been made in the molecular aspects of brain tumors, deciphering a comprehensive role for ATRX in gliomas is still in its infancy." (PMID 29034211, 2017). "Similar to findings in adult IDH1-mutant gliomas, we identify heterogeneous ATRX alterations among IDH1 mutant pHGG tumor pairs." (PMID 29084603, 2017). "The IDH1/2 gene mutations, ATRX loss/mutation, 1p/19q status, and MGMT promoter methylation are increasingly used as prognostic or predictive biomarkers of gliomas." (PMID 27834917, 2016). "The latest evaluation of molecular subgroups of gliomas identified ATRX, CIC, and FUBP1 mutations, and allowed distinguishing patients with IDH1/CIC/FUBP1 or IDH1/ATRX mutations." (PMID 27834917, 2016). "Similar results were seen in LS0082 and SNB19 glioma cells—knocking down ATRX prevented CDK4 inhibitor induced senescence and MDM2 levels did not decrease." (PMID 25803170, 2015). "And several teams demonstrated that ATRX alteration, combined with other classical biomarkers, refined the molecular classification of adult gliomas, providing a prognostic tool for clinicians." (PMID 25971279, 2015).
glioma (continued). "Several previous studies reported various prognostic genes identified via mutation analyses, and ATRX and TERT promoters have recently been recognized as prognostic markers of gliomas." (PMID 26558387, 2015). "In the present study, to examine effect of ATRX on glioma cells, the intrinsic expression of ATRX was repressed by siRNA 589i, 590i and 592i." (PMID 25971279, 2015). "The mutational analysis of 363 brain tumors reported the distribution of ATRX, CIC (homolog of the Drosophila capicua gene), and FUBP1 mutations in gliomas." (PMID 24202337, 2013). "This analysis defined two highly recurrent genetic signatures in gliomas: IDH1/ATRX (I-A) and IDH1/CIC/FUBP1 (I-CF)." (PMID 24202337, 2013). "The recent findings of somatic mutations in key regulatory genes (H3.3, ATRX and DAXX) highlight the importance epigenetic alterations have in the development of glioma." (PMID 22771539, 2013). "By contrast, ATRX was uniformly wild type in the 4 IDH-wild type gliomas featured in our tumor cohort." (PMID 23104868, 2012). "Mutations in ATRX and, to a lesser extent, DAXX have recently been identified in a number of tumor subtypes, including pediatric and adult gliomas." (PMID 23104868, 2012). "In adult primary gliomas, IDH-mutant gliomas are often accompanied by ATRX mutations." (PMID 41008886, 2025). "The results indicated IDH1 mutate, 1P19 codeletion, ATRX and MGMT as robust favorable clinical prognostic indicators, while PCK2 along with age (PCK2, TCGA: P<0.0001, CGGA: P<0.0001) serve as indicators for poor survival time in glioma patients." (PMID 39744481, 2025). "We have thus investigated directly the TMM activated by tumors in a cohort of 100 gliomas from the Pitié-Salpêtrière Tumor bank, including 92 with ATRX mutations (and 8 histone-mutant without NGS information)." (PMID 41422096, 2025). "However, positive expression of the ATRX gene as an independent predictor of preoperative seizures in glioma has been reported." (PMID 40103938, 2025). "Furthermore, experimental ATRX knockout in four telomerase-positive, ALT-negative glioma lines showed that only two lines exhibited ALT features post-ATRX loss, highlighting the need for additional factors beyond ATRX in fully establishing ALT activity." (PMID 40362411, 2025). "Moreover, when ATRX mutations are present, radiotherapy and temozolomide chemotherapy can induce high PD‐L1 expression in IDH‐mutant glioma cells, further exacerbating inhibition of the immune microenvironment and promoting tumor immune escape." (PMID 40264576, 2025). "Similarly, we examined patterns of gene dysregulation in glioma tumour samples and found that downregulation of DRG2 was strongly associated with ATRX-loss in LGG." (PMID 39921567, 2025).
glioma (continued). "They demonstrated that SRH microscopy-based modality is capable of accurately predicting gliomas molecular alterations (IDH mutation, 1p19q co-deletion, and ATRX mutation) intraoperatively, in addition to creating H&E-like images, augmenting this diagnostic technique." (PMID 38325706, 2024). "Furthermore, addition of MR diffusion to conventional MRI features significantly improved the diagnostic value in preoperative prediction of IDH1, MGMT, and ATRX in patients with glioma." (PMID 38486342, 2024). "In this line, a study in pilocytic astrocytomas demonstrates that ALT-positive/ATRX-negative anaplastic pilocytic astrocytomas are a distinct category of gliomas which is associated with worse overall and recurrence/progression-free survival." (PMID 38240992, 2024). "Here, using preclinical models of glioma, the authors show that ATRX inactivation promotes innate immune signalling in response to double stranded RNA-based innate immune agonists, an effect that is masked in IDH-mutant tumours, presenting a therapeutic vulnerability." (PMID 38272925, 2024). "Studies have shown that ALT can develop in the absence of ATRX mutations, rendering ATRX-targeted therapies ineffective for some ALT-positive gliomas, necessitating alternative treatments." (PMID 39479502, 2024). "To explore this, we generated ATRX-deficient glioma models in the presence and absence of the IDH1R132H mutation." (PMID 38272925, 2024). "Even glial tumors that are IDH1 R132H non-mutant but express ATRX, with IDH mutation assessed using molecular testing and 1p19q codeletion, are considered oligodendrogliomas." (PMID 39135755, 2024). "ATRX expression lever vary across different grades of gliomas." (PMID 38898533, 2024). "Taken together, these observations reveal that ATRX inactivation sensitizes glioma cells to dsRNA." (PMID 38272925, 2024). "Grade WHO II/III IDH-mutant gliomas, including oligodendrogliomas (IDH-O) with 1p/19q codeletion and astrocytomas (IDH-A) with intact 1p/19q, show differences in chromatin accessibility and gene expression that correlate with the extent of ATRX loss." (PMID 39479502, 2024). "Accordingly, these data further support the notion that the agonizable state of innate immune signaling in ATRX-deficient glioma exists largely independent of IDH1 mutational status." (PMID 38272925, 2024). "Next, we evaluated the extent to which ATRX inactivation impacts glioma growth in vivo." (PMID 38272925, 2024). "Given the strong association between ATRX/H3.3 and PML-NBs, we sought to determine if pediatric glioma H3.3 mutations might exert oncogenic effects through disruption of PML-NBs, as is the case in APL." (PMID 38066546, 2023).
glioma (continued). "pTERT mutations (namely c.-124C > T) were detected in 12 of 13 ATRX-intact, but none of ATRX-deficient gliomas." (PMID 37891325, 2023). "By comparing the top 20 genes with highest frequency of somatic mutations in low- (n=441) and high-risk (n=203) group, we found that higher frequency of IDH, ATRX, and CIC mutations in gliomas with low LRS risk, while mutations of EGFR, PTEN, and NF1 were more frequent in the high-risk group." (PMID 36860853, 2023). "Additionally, the low-risk group glioma samples possessed more frequent mutations in IDH, ATRX and CIC genes, whose mutations possess anti-tumor effects in gliomas." (PMID 36845382, 2023). "According to our results, these changes are absent or rare in ATRX-deficient gliomas, but several mutations in other HR-related genes were found." (PMID 37891325, 2023). "We further found that inclusion of monoallelic LOF events matched the predictive power for ATRX biallelic LOF in CNS cancers and HERC2 biallelic LOF in skin cancers, suggesting that single genetic hits are sufficient to affect repair and ensuing mutational patterns for these genes." (PMID 36883553, 2023). "ATRX (ATP-dependent helicase) and TERT (telomerase reverse transcriptase) mutations are usually present together and are essential for further differentiation of gliomas." (PMID 34687436, 2022). "Finally, the two groups were also significantly different at the level of somatic mutations, especially in glioma prognosis-related genes such as IDH1 and ATRX, with lower mutation rates in the high-risk group leading to poorer prognosis." (PMID 36226186, 2022). "The mutation frequencies of IDH1 and ATRX in gliomas with a low-risk score were remarkably higher than in gliomas with a high-risk score (IDH1, 92% vs. 31%; ATRX, 33% vs. 21%), while TTN and MUC16 had lower mutation frequencies (TTN, 8% vs. 21%; MUC16, 7% vs. 10%)." (PMID 36311792, 2022). "In contrast, a previous study of 14 cases of multicentric glioma finds no IDH1 mutation or ATRX loss." (PMID 35806978, 2022). "Moreover, lower DDR scores were observed in gliomas with IDH1 and ATRX mutations, but on the other hand, EGFR and PTEN mutations were associated with high DDR scores." (PMID 35720326, 2022). "Interestingly, the four RTKi tested induced higher toxicity to a different extent in the three ATRX KO high-grade glioma cell lines when used at 5 μM and 10 μM." (PMID 35406561, 2022).